IDH1 (isocitrate dehydrogenase (NADP(+)) 1)
Diseases named in the same sentence as IDH1 in open-access papers (continued):
Sharing a sentence is not in itself a finding about the gene and the disease.
tumor (continued). "Second, we did not study the association between IDH-1-mutation and tumor blood flow, which is the goal for our further study." (PMID 35136119, 2022). "These tumours are characterised by the presence and absence of IDH1 and IDH2 mutations, and recently, TERT promoter alterations have been reported in around 20% of cases." (PMID 36042521, 2022). "However, metastases or recurrent disease appeared to occur less frequently in patients with IDH2 G2/3 tumours compared to IDH1 and IDHwt tumours (% metastases/recurrence, IDH1: 37%, IDH2: 13%, IDHwt: 23%, IDH1 vs IDH2: p = 0.04)." (PMID 36042521, 2022). "Interestingly, profiling of the left-sided tumor manifestation revealed a fundamentally different profile: This tumor showed IDH1 and IDH2 wildtype and TERT C228T promoter mutation." (PMID 35018523, 2022). "TMZ was found to be able to reduce expression of IDH1 in patient-derived tumor spheres." (PMID 35626024, 2022). "Based on the mutual support between these studies and our findings, we speculate that the favorable prognosis of the IDH1 mutant group may also be related to the reduction of immune cells capable of maintaining the tumor immunosuppressive environment." (PMID 36245971, 2022). "Besides tumour grade, our results verified that EZH2 immunoexpression was significantly associated with other clinicopathological parameters, such as age and IDH1 R132H protein mutant status." (PMID 36292072, 2022). "The combination of IDH1 expression and other prognostic factors like metastasis of lymph nodes, size of the tumor, differentiation, smoking habits, and gender may improve NSCLC prognosis prediction." (PMID 36552994, 2022). "Recent studies indicate that these neurotransmitters have tumor-promoting features; thus, this might help to further explain the unfavorable prognosis of IDH1-WT compared with IDH1-mut diffuse glioma." (PMID 34941573, 2022). "In other words, tumor cells are the main source of MT1-MMP in gliomas with diffuse IDH mutations, which provides a basic theoretical basis for this study to analyze the relationship between MT1-MMP and IDH1 at the histological level." (PMID 35350840, 2022). "However, it should be noted that the timing of the IDH1 and IDH2 mutations in the evolution of the tumour cannot be ascertained from the information at hand." (PMID 36286062, 2022). "The histology showed a tumor with fibrillary background and increased cellularity, with pleomorphic cells but without microvascular proliferation or necrosis; the immunohistochemical study was positive for GFAP and IDH1 R132H mutation." (PMID 35884525, 2022). "We found that age, sex, cancer recurrence, WHO tumor grade and isocitrate dehydrogenase 1 (IDH1) mutation were without difference in patients with or without Tmod3 cleavage." (PMID 35765111, 2022). "In line with this, the molecular landscape of human iCCA includes a subgroup of tumours with oncogenic IDH1 and IDH2 mutations; genetic variants which are not observed in extrahepatic biliary tract tumours." (PMID 35986087, 2022). "More than half of LGG tumours were IDH1 R132H mutants, but only two HGG were IDH1 R132H mutants." (PMID 36050369, 2022).
tumor (continued). "The age at diagnosis for each IDH group was similar for ACT/G1 and DD CS, and the difference in age of the G2/3 tumours explained the overall difference in ages (median age G2/3, IDH1: 60 year, IDH2: 71 year, IDHwt: 44 year, IDH1vs IDH2: p = 0.04, IDH1 vs IDHwt: p = 2e−6)." (PMID 36042521, 2022). "We also found that methylation profiles distinguish IDH1- from IDH2-mutant tumours." (PMID 36042521, 2022). "She underwent a biopsy, and the secondary tumor was diagnosed as GBM with IDH1/2 wild-type." (PMID 35505351, 2022). "An earlier study has shown that knockdown of wild-type IDH1 triggers a set of tumor suppressor genes, including NDUFS1 (murine Ndufa9), which when mutated is implicated in low survival in certain cancers, and there is a report of high expression of WT-IDH1 in H3K27M tumors." (PMID 35395831, 2022). "As it is known that 2HG exerts diverse biological functions including regulation of DNA hydroxymethylation, it is feasible that the IDH1 and IDH2 mutations explain our different methylation array findings and mediate the different behaviour of the tumour subgroups." (PMID 36042521, 2022). "By immunohistochemistry (IHC), IDH1-positive tumor cells and Ki-67 of 5% were observed." (PMID 35991838, 2022). "Preclinical studies have evidenced that inhibiting IDH1 may stimulate anticancer immunity through the conversion of an immunologically “cold” milieu to “hot”, as well as by determining the restoration of tumor cells’ sensitivity to immunological signals." (PMID 36142781, 2022). "Genetic analysis for tumor IDH1 mutational status and 1p/19q status was available for 57 patients: 20 patients were IDH1wt (35.1%), 19 were IDH1-mutant but had no 1p/19q codeletion, (33.3%), and 18 were IDH1-mutant and 1p/19q codeleted (31.6%)." (PMID 33986314, 2021). "Next, we explored the correlation between B2M mRNA expression and tumor grade or IDH1 phenotype." (PMID 33960680, 2021). "Samples without mutation(s) in the corresponding tumor were determined as WT in CSF cfDNA for IDH1 R132H (n = 16), pTERT C228T (n = 22) and C250T (n = 32), and H3 K27M (n = 32) assays." (PMID 33417137, 2021). "This trial allowed a mixture of patients with different tumour grades, different disease stages (advanced, recurrent tumours and inoperable tumours), and did not sub-stratify patients by molecular markers, such as IDH-1 mutation." (PMID 34094937, 2021). "Importantly, we verified the effect of IDH1 on HIF-related proteins through IHC in tumor-bearing mice." (PMID 33867843, 2021). "Therefore, patients bearing wild-type IDH1 and tumor-SVZ distance from 0 to 10 mm displayed poorer OS and PFS." (PMID 34490090, 2021). "Using quantitative PCR changes in wildtype IDH1 levels can also be used to monitor tumor burden and treatment response when the tumor does not have an IDH-1 mutation." (PMID 34771592, 2021). "IDH1 wild type and tumor-SVZ distance from 0 to 10 mm suggest poorer OS and PFS." (PMID 34490090, 2021). "In addition, IDH1 regulates hypoxia-inducible factors related to tumor angiogenesis and invasiveness." (PMID 34389754, 2021).
tumor (continued). "Isocitrate dehydrogenase 1 wildtype (IDH-1 wt) was observed in 68 patients (94%) with a high edema to tumor ratio and in 57 patients (79%) with a low edema to tumor ratio (p=0.01; 95%CI: 0.07-0.71, OR: 0.2 in univariate and p=0.03; 95%CI: 0.13-0.90, OR: 4.6 in multivariate analysis." (PMID 33868245, 2021). "Therefore, IDH1 and hBCATm metabolism can be proposed to work in conjunction to support tumour growth in luminal A tumours." (PMID 33367952, 2021). "The consumption of NADPH by mutant R132H IDH1 may account for a metabolic vulnerability that sensitizes tumor cells to ionizing radiation." (PMID 33808242, 2021). "Multivariate Cox regression analysis adjusted for age, gender, tumor grade, and tumor sites confirmed the negative impact of IDH1/2 mutations on patient overall survival (HR = 1.90; 95% CI = 1.06–3.42; p = 0.03)." (PMID 34085407, 2021). "As IDH1 and IDH2 mutations occur early in the evolution of the disease and appear to be retained if the tumour transforms into higher grade disease, we considered that they could be exploited as biomarkers for clinical outcome." (PMID 34528398, 2021). "For IDH1 mutation status, patients with wild-type IDH1 were not significantly different from those with mutant-type IDH1 in tumor purity." (PMID 34925437, 2021). "Moreover, IDH1 strong IRS class also associated with lower TNM staging, in 52.9% of stage I tumours." (PMID 33367952, 2021). "We have corroborated our in vitro cytotoxic studies with in vivo xenograft models, where we observed a significant delay in tumor growth, using both the engineered HCT116 IDH1-mutant xenograft model, as well as the fibrosarcoma HT1080 xenograft model with an endogenous IDH1 R132C mutation." (PMID 34027408, 2021). "Sequencing analysis revealed a heterozygous IDH1 R172G mutation in tumor tissue, whereas this mutation was absent in germline DNA." (PMID 34616365, 2021). "NADPH production is impaired in gliomas with IDH1 mutations, which may sensitize the tumors to radiation and chemotherapy, explaining why patients with IDH mutant neoplasms live longer." (PMID 34638714, 2021). "The combination treatment caused a significant delay in tumor growth relative to Olaparib or AZD6738 alone in the HCT116 IDH1-mutant flank model without any significant change in body weight." (PMID 34027408, 2021). "Consistent with the IHC and NGS results, both LG and HG F48 tumor components expressed IDH1-R132H." (PMID 33853673, 2021). "B2M expression was correlated with tumor grade and was downregulated in IDH1 mutant samples." (PMID 33960680, 2021). "The IDH1 (R132H) mutation had no significant impact on expression status of eIF3I or eIF4H positive tumor cells.Error bars are partly missing because of the low number of samples or similar tissue intensity scores in the immunohistochemical evaluation." (PMID 33807050, 2021). "Epigenetically regulated mRNAsi, a stemness index, shows a negative correlation with tumor pathology and clinical features which mainly results from a high frequency of IDH1/2 mutations and resulting DNA hypermethylation." (PMID 34888308, 2021). "The mutation of IDH1 or IDH2 leads to the elevated production of the oncometabolite 2‐hydroxyglutarate, which is thought to induce significant epigenetic alterations and promote the initiation and progression of tumor cells." (PMID 33459509, 2021). "In this study we investigated three different mutant IDH1 tumor models." (PMID 33668509, 2021). "In hypoxic tumor cells, IDH1 and IDH2 mediate the reversal of the TCA cycle." (PMID 33727360, 2021).
tumor (continued). "Likewise, the only one IDH1 mutant tumor in our dataset had low RAD51 levels, while the patient with equivocal IDH1 staining had relatively high RAD51 levels." (PMID 34771522, 2021). "A similar experiment comparing BT142 (mutIDH1R132H) with U87 (WT IDH1) cells in cell culture and mouse tumor models showed that there is significantly less labeled lactate in mutIDH1 compared with WT IDH1 cells after perfusion with hyperpolarized [1-13C]-pyruvate." (PMID 35028610, 2021). "Five mutations in PIK3CA, one in BRCA1 and one in IDH1 found in this study are FDA-recognized biomarkers (level 1) and one ERBB2 mutation is a standard care biomarker (level 2A), predictive of response to FDA-approved drugs in specific tumor types." (PMID 33500480, 2021). "Next, we explored the effect of IDH1 on tumor growth in CRC cell lines." (PMID 34234856, 2021). "Additionally, they were able to quantify the number of mutant IDH1 transcripts, which directly correlated with tumor burden." (PMID 33925295, 2021). "From an immunological perspective, IDH1(R132H) represents a potential immunotherapy target because it is a tumor-specific potential neoantigen that is indeed presented in major histocompatibility complex class II (MHCII) and can, thus, evoke a robust immune response in CD4+ T cells." (PMID 34203535, 2021). "In all cases, the tumours also contained a sharply defined well‐differentiated cartilaginous component, the diagnostic hallmark of a dedifferentiated CHS, and two cases harboured IDH1 mutations (cases 360 and 382)." (PMID 33949149, 2021). "In patients with G2 and G3 tumours, OS differed significantly between patients with and without IDH1 mutation (log-rank p-value in G2: 0.002; in G3: 1E-11; in G4; 0.02)." (PMID 34205437, 2021). "We report that tumours harbouring IDH1R132H mutations, regardless of tumour type, have lower genome-wide DNA methylation levels compared to those harbouring other IDH1/2 hotspot mutations (‘non-IDH1-R132H IDH1/2-mutated tumours’)." (PMID 33740099, 2021). "Prolonged presence of mutant IDH1 renders most of these modifications irreversible, which may have critical importance for tumor progression." (PMID 34356864, 2021). "Targeted next generation sequencing panel revealed a TERT promoter mutation (VAF 55%) identical to the peri-rolandic lesion and an IDH1 R132G mutation (VAF 46%) not seen in the patient’s supratentorial tumor." (PMID 34587990, 2021). "In addition, WHO grade IV (p = 0.001), SVZ involvement (p = 0.002), tumor-SVZ distance from 0 to 10 mm (p = 0.02), chemotherapy (p = 0.02), and IDH1 mutation (p = 0.03) served as independent predictors for patient PFS." (PMID 34490090, 2021). "Finally, IDH1 substrate α-KG was used for in vivo experiments, and the results showed that α-KG also had a significant inhibitory effect on tumor size and weight in tumors bearing mice." (PMID 33867843, 2021). "In the IDH1 wild-type background, degradation of keratan sulphate, which can interact with neuroregulatory ligands, dissolution of fibrin clot, and crosslinking of collagen fibrils, which are important for tumour cell and T cell migration, were higher than those in the IDH1 mutant." (PMID 34205437, 2021). "Methylation of MEOX2 promoter correlated with IDH1 mutation status and was independent of tumor grade (WHO, 2016 classification) (p < 0.001)." (PMID 34885053, 2021). "Thus, IDH1 and IDH2 mutations represent an early event in the development of central cartilaginous tumours." (PMID 31728625, 2020). "Molecular aberrations involving various driver mutations including ALK, ROS1, KRAS, IDH1/2 and JAK2 may impact thrombotic risk in various tumor types." (PMID 32707653, 2020). "Moreover, the inhibition of the mutant IDH neomorphic enzymatic activity improves the anti-tumor immunity of the IDH1-specific vaccine." (PMID 32825279, 2020). "FLT uptakes in IDH1-wildtype tumours were significantly higher than those in IDH1-mutant tumours." (PMID 32382870, 2020).
tumor (continued). "Whereas none of the Mongolian HCC tumor samples was found to carry mutations in IDH1 or IDH2, we observed a subset of 9 samples in the Mongolian cohort that appears to carry TCGA’s IDH-like gene signature." (PMID 32873799, 2020). "Because our models were trained purely with radiomic features, future work may focus on studying the relationship between these quantitative radiomic features and tumor heterogeneity across IDH1 genotypes." (PMID 33121211, 2020). "The high LINC00511 expression group was more positively correlated with larger tumour size (P = .026), wild‐type IDH1/2 (P = .043), recurrence (P = .011) and poor prognosis than the low LINC00511 expression group, however, not with other features such as gender (P = .157) and age (P = .7)." (PMID 31856394, 2020). "There was a significant overlap of MET T/N ratios between IDH1-mutant and IDH1-wildtype tumours." (PMID 32382870, 2020). "ROC analysis for differentiating IDH1-mutant tumours from IDH1-wildtype tumours showed that the area under the curve (AUC) of the FLT T/N ratio (AUC 0.911, 95% CI 0.847–0.975) was significantly larger than that of the MET T/N ratio (AUC 0.727, 95% CI 0.607–0.847) (P < 0.01)." (PMID 32382870, 2020). "In the 52 IDH1-wildtype tumours, there was only 1 IDH1-wildtype DA." (PMID 32382870, 2020). "Finally, molecular analysis of the tumours revealed that this ion channel signature harnessed a mesenchymal subtype and wild-type IDH1 preference." (PMID 33096667, 2020). "This hypothesis was supported by experimental studies showing that the ATRA+ATO treatment is synergistic in its anti-tumor effects in a number of mouse and human mutant IDH1/IDH1 leukemic models." (PMID 32859092, 2020). "The issue regarding the usefulness of FLT-PET/CT for differentiating IDH1 mutation status in non-enhancing tumours should be addressed with more cases in the future." (PMID 32382870, 2020). "Immunohistochemical stains could also be helpful to identify tumor heterogeneity of the IDH1 p.R132H mutant." (PMID 32333643, 2020). "In the present study, there were only 2 IDH1-mutant GBMs among the 29 IDH1-mutant tumours." (PMID 32382870, 2020). "To determine if the observed heterogeneity was a direct consequence of established molecular subtypes in GBM, we performed cross-platform analyses using RNA (expression profiling) and DNA (IDH1 mutation and MGMT promoter methylation) isolated from matched tumor tissue." (PMID 32312953, 2020). "IDH1 mutation leads to the increase of 2-hydroxyglutarate (2-HG), and the loss of 5hmC is partly mediated by the decrease 2-HG dehydrogenase (L2-HGDH), which has tumor inhibitory effects." (PMID 33282735, 2020). "The disagreement in this regard may be due to the mixture of different tumor types in the IDH1-wild-type group in our study." (PMID 32856857, 2020). "IDH1-wildtype tumours showed significantly higher FLT uptake than IDH1-mutant tumours." (PMID 32382870, 2020). "The observations of less than 5% VAF of the IDH1 mutation in cases 3, 5, and 6 in a contexts of 51%‐70%, 31%‐50%, and 41%‐60% estimated tumor cellularity and 33%, 13%, and 18% VAF of the coexisting EGFR, KRAS, or PIK3CA mutation suggest presence of IDH1 mutation in a tumor subpopulation." (PMID 32333643, 2020). "In addition, studies have shown that an IDH1-specific titanium vaccine can antagonize IDH1-expressing tumor cells and reduce the growth of intracranial tumors." (PMID 33163535, 2020). "The downstream functional effects of R-2HG administration in IDH1 or 2 wild type cells were all anti-tumour ones, and the results of the experiments had also important implications regarding the possibility of combining R-2HG with standard chemotherapy in IDH1/2 wild type tumours." (PMID 32316617, 2020). "Intra-operative rapid determination of tumour IDH1 status could therefore inform neurosurgical decision-making." (PMID 33302429, 2020).